IDH2 (isocitrate dehydrogenase (NADP(+)) 2)
Diseases named in the same sentence as IDH2 in open-access papers (continued):
Sharing a sentence is not in itself a finding about the gene and the disease.
cancer (continued). "The most clinically advanced example of targeting an oncometabolite is the inhibition of mutant IDH1 and IDH2 enzymes, which drive cancer through the aberrant production of 2-HG." (PMID 40931345, 2025). "Since the knockdown of IDH2 caused a significant increase of α-KG in TNBC cells, we thus investigated the direct impact of α-KG on cancer cell growth and viability using multiple assays." (PMID 38658533, 2024). "Reductive carboxylation from Gln-derived 2OG via IDH1 or IDH2 has been observed in brown adipose tissue and in cancer cells under deep hypoxia or with defective mitochondria." (PMID 39057706, 2024). "This commentary explores three recent investigations focusing on the role of wild-type IDH2 in cancer and immune cell function." (PMID 39409901, 2024). "The three studies’ collective findings underscore the significant therapeutic potential of targeting wild-type IDH2 in cancer treatment and immunotherapy." (PMID 39409901, 2024). "To investigate the mechanism through which IDH2 affects polarization in macrophages co-cultured with cancer cells (LLC1), we analyzed the expression of polarization-specific protein markers using Western blot analysis." (PMID 39256649, 2024). "Collectively, these reports highlight wild-type IDH2 as a promising therapeutic target, with potential applications as a two-edged sword in both cancer treatment and immunotherapy." (PMID 39409901, 2024). "The studies highlighted in this commentary demonstrate the significant role of wild-type IDH2 in both cancer progression and immune cell function." (PMID 39409901, 2024). "IDH1/2 mutations that are associated with cancer tend to localize to the arginine (R) residue that is crucial for the recognition of isocitrate (R132 for IDH1, R140 or R172 for IDH2), with a vast majority of IDH1 R132H events." (PMID 38339779, 2024). "IDH1 and IDH2 are also involved in glutamine metabolism, which is important in tumorigenesis as glutamine deprivation suppresses cancer growth." (PMID 39876890, 2024). "The implications of these studies extend beyond TNBC, potentially offering new therapeutic avenues for a broader range of cancers reliant on IDH2 activity, both as standalone therapies and in combination with other treatments." (PMID 39409901, 2024). "Together, these data suggest that ROS generation was likely an important mechanism contributing to the cancer cell death induced by cisplatin and abrogation of IDH2." (PMID 36831011, 2023). "While the role of the mutant IDH2 in cancer has been well characterized, recent studies have shown there is a pro-tumorigenic role for wild-type IDH2 as well." (PMID 37601653, 2023). "Mitochondrial NADP+-dependent IDH2 is a major enzyme that produces NADPH, which is a crucial driver of mitochondrial GSH turnover, and downregulation of IDH2 sensitizes cancer cells to erastin-induced ferroptosis." (PMID 37580393, 2023). "Instead, we found that IDH2 expression was elevated and promoted cancer cell resistance to cisplatin." (PMID 36831011, 2023). "Ivosidenib (AG-120) and enasidenib (AG-221) are now approved for treatment of IDH1- and IDH2-mutant cancers, respectively." (PMID 37705055, 2023). "Of these genes, GNAQ, GNAS, and JAK2 are associated with cell growth-related factors, whereas NRAS, IDH2, and CTNNB1 are cancer-related genes." (PMID 36780540, 2023). "For example, researchers found causation between mutations in IDH1, IDH2 and TET2—which negatively affect DNA hydroxymethylation rates—and CIMP in leukemia, gliomas and several other cancer types." (PMID 35134107, 2022). "IDH1 and IDH2 mutations result in active site substitutions that profoundly affect IDH activity, cellular metabolism, and cancer development." (PMID 36497259, 2022). "Recent evidence supports that NAD+-dependent protein deacetylase, SIRT3, increases IDH2 activity via deacetylation in cancer cells." (PMID 36497259, 2022).
cancer (continued). "General attention paid to mitochondrial nuclear-encoded gene mutations has greatly emerged since the defects of fumarate hydratase, succinate dehydrogenase, isocitrate dehydrogenase 1 (IDH1), and IDH2 in cancer cells were established." (PMID 36557887, 2022). "In these cancers, IDH1 and IDH2 variants are thought to alter the catalytic function of the mutant enzymes, leading to the production of the oncometabolite D-2-hydroxyglutarate (D-2HG) from α-ketoglutarate (α-KG)." (PMID 36480544, 2022). "IDH mutations linked to cancer are most commonly found in the arginine residue, which is required for isocitrate recognition (R132 for IDH1, R140, or R172 for IDH2)." (PMID 35769466, 2022). "Mutations in the two isocitrate dehydrogenase enzymes involved in cytoplasmic (IDH1) and mitochondrial (IDH2) conversion of alpha-ketoglutarate to D-2-hydroxyglutarate have been described as mutually exclusive in many of these cancer types." (PMID 36304962, 2022). "New tumor entities previously classified as SNUC include SMARCB1-deficient carcinoma, SMARCA4-deficient carcinoma and possibly also IDH2 mutant SNUC." (PMID 36140305, 2022). "Cancer-associated mutations have been identified in two of the three existing isoforms: IDH1 and IDH2, which are mutually exclusive." (PMID 36045702, 2021). "Cancer-associated mutations typically involve heterozygous mutations within the active sites of IDH1 (IDH1)R132H and mitochondrial IDH2 (IDH2)R140Q and (IDH2)R172K." (PMID 33572577, 2021). "In 2017, the FDA approved the first cancer metabolism drug enasidenib, an IDH2 inhibitor, for which the main indication is relapsed and refractory AML." (PMID 35004688, 2021). "Activation of reductive TCA cycle metabolism of glutamine and glutamate via conversion to α-ketoglutarate by the glutamate dehydrogenase reaction and flux to citrate via IDH2 has been invoked as a pathway for synthesis of biomass in growing cancer cells." (PMID 33762012, 2021). "In less than 10 years from the original discovery of cancer-associated IDH1 and IDH2 mutations, first-in-class mutant IDH1 and IDH2 are now clinically available for patients with AML harboring these mutations." (PMID 34083508, 2021). "At present, small molecular inhibitors of IDH1 and IDH2 mutant have been developed, and promising progress has been made in preclinical and clinical development, showing encouraging results in patients with IDH2 mutant cancers." (PMID 33981605, 2021). "The enzymes of TCA cycle, IDH1 and IDH2, are frequently mutated in glioblastoma multiforme and AML, thereby providing the clinical possibility to target these cancers." (PMID 33673109, 2021). "The most common cancer mutations involve the IDH1 and IDH2 isoforms and resulted to be mutually exclusive." (PMID 34070384, 2021). "To confirm the catalytic function of the IDH2 mutant in cancer tissue, we performed the mass spec measurement on D-2-HG in frozen cancer tissue." (PMID 34616365, 2021). "Cancer-related IDH1 and IDH2 mutations occur almost entirely on different arginine residues at the active site of the enzyme." (PMID 33981605, 2021). "GSK864 and AGI-6780 are small molecules that selectively inhibit the cancer-associated mutants of IDH1 and IDH2/R140Q, respectively." (PMID 34876568, 2021). "Mutations in isocitrate dehydrogenase (IDH1) and isocitrate dehydrogenase 2 (IDH2) represent a different group of cancer-related genetic alterations responsible for regulating the activity of α-ketoglutarate-dependent-dioxygenases." (PMID 34201149, 2021). "In cancer metabolism, the role of IDH2 has been reported to guard the redox balance in the cancer cells." (PMID 33455080, 2021).
cancer (continued). "After FDA approval of enasidenib, a first-in-class drug targeting cancer metabolism via inhibition of IDH2 activity, more studies were conducted with R-2-HG positioned as an oncometabolite." (PMID 32943735, 2020). "A well-known function of mutant IDH2 has been demonstrated in cancers such as glioma, cholangiocarcinoma, and breast solid papillary carcinoma with reverse polarity (SPCRP)." (PMID 31599393, 2020). "Mutated IDH1 and IDH2 are incapable of forming α-ketoglutarate and 2-hydroxyglutarate, thereby inhibiting TET protein activity and stimulating the development of cancer." (PMID 32328088, 2020). "The variants in cancer driver genes, MSH6, POLQ, ARID5B, and IDH2, warrant further study to determine the mechanism by which these variant affect cancer progression." (PMID 32066500, 2020). "Deep valleys followed by the highest growth peaks corresponded with close approximation to the three missense mutations from known cancer genes (IDH1, IDH2, and FLT3, p value < 2.2e−16)." (PMID 32024824, 2020). "IDH1 and IDH2 mutations decrease NADPH and GSH levels, leading to enhanced PI3K-AKT-mTOR signaling pathway activity and cancer cell migration." (PMID 32548570, 2020). "Cancer-associated mutations in IDH1 and IDH2 detected in a wide range of human cancers can result in neomorphic enzymes producing 2-HG, instead of α-KG, resulting in global epigenetic changes due to inhibition of JMJDs as well as TET enzymes." (PMID 32217072, 2020). "IDH2 gene expression was found significantly downregulated in early stage (in situ carcinoma) but upregulated in advanced stage (infiltrating carcinoma) colorectal cancer (CRC) compared to peritumor tissue." (PMID 31010244, 2019). "The most common IDH mutation found in cancer is the substitution of a single arginine in the catalytic site of the enzyme, R132 in IDH1 and R140 or R172 in IDH2, which results in a gain of function." (PMID 31817761, 2019). "In conclusion, mutations in mitochondrial metabolic enzymes, IDH2, SDH or FH, results in abundant oncometabolites and leads to epigenetic changes, further dysfunction of mitochondria, production of ROS, cancer progression and notably, increased EMT." (PMID 30909478, 2019). "The acetylation-impacting genes, IDH2, SDHA/B/C, and FH, are annotated as being frequently mutated in cancers in the COSMIC database." (PMID 30823893, 2019). "The genes ACLY, CS, RPE, and IDH2 were found to be among the top 10% of the genes that were frequently overexpressed across 19 cancer types from a meta-analysis study of 1981 tumors (FDR p value < 0.05)." (PMID 30823893, 2019). "We characterized three predominant IDH2 mutants (R172K, R172M, and R140Q) that are often detected in cancer." (PMID 31105869, 2019). "Cancer-associated heterozygous mutations in IDH1 and IDH2 result in the formation of wild-type-mutant heterodimers with neomorphic activity, allowing the reduction of α-KG to 2-hydroxyglutarate (2HG) in the presence of NADPH." (PMID 29342092, 2018). "Mutations in genes associated with key metabolic pathways (e.g., isocitrate dehydrogenase 1 and 2, IDH1/IDH2) are important drivers of cancer, including central nervous system (CNS) tumors." (PMID 30170631, 2018). "In particular, the accumulation of 2-HG is a well-known hallmark in cancer cells and is generally attributable to the occurrence of gain-of-function mutation in IDH1 and IDH2." (PMID 29434411, 2017). "Differences on the importance of IDH1 as compared to IDH2 have been reported for various cancer cell types." (PMID 28806730, 2017). "As a control, we utilized a primary human keratinocytes; interestingly, IDH2 mRNA levels remained unchanged in these non-cancerous cells despite AZD1775 treatment, suggesting a cancer specific regulation of IDH2 by pY37-H2B/WEE1 signaling axis." (PMID 29290954, 2017). "In these cancers, IDH2 inhibition would induce mitochondrial oxidative stress and, probably, priming to proapoptotic stimuli." (PMID 28649560, 2017).
cancer (continued). "In cancer cells with prevailing reductive carboxylation of α-ketoglutarate by IDH2, GDH1-derived NADPH is consumed to support this reaction." (PMID 28649560, 2017). "Enhanced NADPH consumption by the reverse IDH2 reaction thus provides a selective advantage to cancer cells by promoting oncogenic epigenetic alterations and HIF activation." (PMID 28649560, 2017). "The mutations of RAS (KRAS and NRAS), IDH2, EGFR, and PI3K are clinically relevant and well associated in many other cancers." (PMID 28900470, 2017). "The two isoforms, which are mutated in cancer, IDH1 and IDH2, utilize this catalytic process in additional contexts including metabolism and glucose sensing (IDH1) and regulation of oxidative respiration (IDH2)." (PMID 26782057, 2016). "Mutations of IDH1 and IDH2 have great impact on the development and progression of AML and are attractive targets for cancer treatment." (PMID 27577048, 2016). "Despite their different physiological characteristics, most genomic studies of the molecular landscapes in human cancer have frequently combined IDH1 mutations and IDH2 mutations as a single functional group." (PMID 27245697, 2016). "The most common cancer mutations map to single arginine residues in the catalytic pockets: IDH1 (R132) and IDH2 (R172 or R140)." (PMID 26812134, 2016). "We investigated the function of D-2-HG in tumorigenesis using IDH1 and IDH2 mutant cancer cell lines." (PMID 25825982, 2015). "Our data link D2HGDH to cancer and describe an additional role for the enzyme: the regulation of IDH2 activity and α-KG-mediated epigenetic remodelling." (PMID 26178471, 2015). "A variety of human cancers, including AML, show recurrent missense mutations in IDH1 and IDH2 that endow the mutant protein with the ability to synthesize 2-hydroxyglutarate (2HG) from αKG." (PMID 25632305, 2015). "For example, some cancer cells harbor mutations in TCA enzymes (e.g., FH, SDH, IDH2) or regulatory proteins that control mitophagy (i.e., LKB1)." (PMID 25621173, 2015). "To determine the function of D-2-HG in cancer cells, we aimed to eliminate D-2-HG in human cancer cells that contain a mutant IDH1 or IDH2 allele." (PMID 25825982, 2015). "This study aims to investigate the potent lead TCM candidates for IDH2 R140Q mutant protein inhibitors against cancers." (PMID 24995286, 2014). "Mutations in these genes appear to be either specific to ICC, as is the case of IDH1 and IDH2 (p=0.0005), or cluster within this cancer type as is the case for ARID1A, BAP1, and PBRM1 that were found in 34.3% (24/70) of ICC." (PMID 24867389, 2014). "The expression of 5-hydroxymethylcytosine (5-hmC) and isocitrate dehydrogenase 2 (IDH2) is frequently downregulated in numerous cancers." (PMID 24716838, 2014). "But the opposite enantiomer – the (R)-enantiomer, accumulates in adult cancer patients with somatically acquired mutations in IDH1 and IDH2." (PMID 24581008, 2014). "The high NADP+-dependent IDH activity in E478 suggests that the cancer cells compensate the IDH1 defect by upregulating the activity of the mitochondrial IDH2." (PMID 24252742, 2013). "Various investigators working in the field of cancer genetics identified an increased incidence of heterozygous mutations in isocitrate dehydrogenase 1 and 2 (IDH1, IDH2) in selected individuals with carcinoma." (PMID 22391998, 2012). "This reverse IDH2 reaction has been demonstrated in cancer cells and obviously also occurs in J774A.1 cells." (PMID 23285016, 2012). "We found that in the first three steps of the TCA cycle, digital expression of aconitase 2 (ACO2) in the brain exceeded both citrate synthase (CS) and isocitrate dehydrogenase 2 (IDH2), while in cancer cells this trend was quite the opposite." (PMID 22166000, 2011). "Based on this, cancer cells that have heterozygous IDH1 or IDH2 mutations would be expected to contain a mixture of WT:WT, WT:mutant, and mutant:mutant IDH1 or IDH2 dimers." (PMID 21326614, 2011).
cancer (continued). "We show by coprecipitation that five cancer-derived IDH1 R132 mutants bind IDH1-WT but that three cancer-derived IDH2 R172 mutants exert minimal binding to IDH2-WT." (PMID 21326614, 2011). "Collectively, our findings suggest that IDH2 may play a protective role during the early stages of cancer development, offering a fresh perspective for cancer research." (PMID 41258072, 2025). "In cancers, mutations in IDH1 or IDH2 can result in the formation of D-2-hydroxyglutarate (2-HG)." (PMID 41235226, 2025). "D-2-HG is produced by neomorphic activity of mutant IDH1 or IDH2 enzymes in several cancers." (PMID 40931345, 2025). "Many cancer studies already focused on IDH1 and IDH2 mutations." (PMID 39858052, 2025). "However, cancer-associated mutations, most commonly IDH1-R132H or IDH2-R140Q/R172K, confer a neomorphic enzymatic function." (PMID 40724998, 2025). "The presence of IDH mutations provides alternative therapeutic options including selective small molecule inhibitors (e.g. Enasidenib for IDH2 mutations and Ivosidenib for IDH1 mutations) which inhibit DNA hypermethylation and lead to delayed cancer cell growth and induction of cell differentiation." (PMID 38491228, 2024). "Thus, we propose that IDH2 plays an important role in determining the fate of macrophage polarization and influences cancer progression." (PMID 39256649, 2024). "Compared with WT macrophages, OXPHOS complex I and II were suppressed in IDH2-deficient macrophages regardless of co-culturing with cancer cells." (PMID 39256649, 2024). "IDH2 is also overexpressed in cancer, lowering ROS and increasing the growth of cancer cells." (PMID 38674143, 2024). "Our findings further address the possibility of D-mannose as a drug for cancer treatment, and may contribute to the exploration of IDH2 targeted therapies." (PMID 38167476, 2024). "This is probably due to the nature of the mutations, which, unlike IDH1 and IDH2 mutations, are primarily inactivating mutations and, therefore, do not result in the cancer cell acquiring new functions." (PMID 39063158, 2024). "This research underscores the urgent need for specific inhibitors targeting wild-type IDH2, which could revolutionize cancer immunotherapy and broaden treatment options for various cancer types." (PMID 39409901, 2024). "It seems that cancer cells could sense the suppression of the TCA cycle due to IDH2 abrogation, and enhance glutamine uptake and its flux into the TCA cycle as a compensatory response." (PMID 38658533, 2024). "Almost all cancer cell colonies were eliminated by shRNA knockdown of IDH2 in combination with 2 μg/mL cisplatin, which by itself (cisplatin) could only inhibit 65% of the colony formation." (PMID 36831011, 2023). "Additionally, in lung cancer cells, the overexpression of IDH2 decreases α-KG concentrations, enhances the production of 2-HG, and decreases ROS levels, protecting cancer cells against DNA damage." (PMID 37601653, 2023). "IDH2 mutant inhibitors will probably improve the clinical treatment of certain cancer type." (PMID 36418670, 2023). "Furthermore, we identified NADBPs that are known (ATIC, AR and IDH2),as well as potential new drug targets in cancer (FH and NT5C2)." (PMID 36880517, 2023). "Cancer-associated mutations in IDH1 and -2 are typically heterozygous and result in substitution of arginine residues within the enzymes’ active site (most commonly R132 of IDH1, or R140 or R172 of IDH2)." (PMID 37526143, 2023). "In colorectal cancer, wild-type IDH2 protects cancer cells against ROS-mediated DNA damage." (PMID 37601653, 2023). "Interestingly, the nature of the various IDH substitutions differs among the cancer types, i.e., IDH1 is more frequently mutated in solid tumours, while IDH2 is mainly mutated in some blood cancers." (PMID 37296846, 2023).